SSTR2 (somatostatin receptor 2)
Diseases named in the same sentence as SSTR2 in open-access papers (continued):
Sharing a sentence is not in itself a finding about the gene and the disease.
meningioma (continued). "The suggested radiotracer makes use of markers with a high affinity for SSTR-2, and is therefore highly effective in tumors such as carcinoids and meningiomas, which have a high expression of SSTR-2." (PMID 40710005, 2025). "SSTR-2 has been reported to be expressed in 64–100% of meningiomas, making it an interesting target for NIR-PIT." (PMID 40430568, 2025). "In stark contrast, somatostatin receptor 2 (SSTR2) is ubiquitously expressed in meningiomas and was formerly targeted with somatostatin analogs with modest success." (PMID 40149634, 2025). "[68Ga]-DOTATATE, a positron emission tomography (PET) radiotracer targeting somatostatin receptor 2 (SSTR2), has demonstrated superior clinical utility compared to MRI alone in identifying residual meningioma after surgery." (PMID 41497451, 2025). "Overexpression of the somatostatin receptor subtype 2 (SSTR2) on meningiomas has been broadly confirmed." (PMID 41091274, 2025). "IMPLICATIONS FOR PATIENT CARE: PRRT in heavily pretreated and progressing meningioma patients overexpressing SSTR2 showed good disease control, making this a treatment option for this orphan disease." (PMID 39142827, 2024). "Membranous and cytoplasmic staining were observed most frequently (SSTR1, 43%; and SSTR2, 71%) in canine meningiomas." (PMID 39011594, 2024). "IHC of 7 canine and 12 feline meningiomas utilizing antibodies against SSTR1 and SSTR2 revealed immunoreactivity in all feline and canine meningiomas." (PMID 39011594, 2024). "It is noteworthy to mention that most current PET-studies involving meningiomas focus on the value of PET tracers targeted to the somatostatin receptor 2 (SSTR-2), like 68Ga-DOTATOC PET and 68Ga-DOTATE PET." (PMID 38720053, 2024). "Due to a paucity of literature supporting the role of PET with SSTR2 targeted tracers in meningioma FU, future studies will have to prove its definitive value." (PMID 38720053, 2024). "DOTA PET/CT supports accurate tumor recognition in meningioma and PitNET and is recommended in SSTR2-expressing tumors planned for treatment with highly conformal radiation." (PMID 38791956, 2024). "Rapid decreases in the expression of SSTR2 and other hormone receptors such as progesterone receptor (PR) during culturing of primary meningioma cells have been reported before." (PMID 39061156, 2024). "In this investigation, SSTR1 and SSTR2 detection rates in IHC were 100% in meningioma samples from both species." (PMID 39011594, 2024). "In meningioma, all five receptors are well expressed in a receptor-specific manner with SSTR2 as a major receptor subtype; however, the expression of SSTR5 was relatively higher in benign than malignant meningioma." (PMID 38203605, 2023). "Taken together, widespread distribution of SSTR2 in meningioma implicates SSTR2 radiolabeled ligand in the diagnosis of meningioma." (PMID 38203605, 2023). "We previously showed the mRNA expression of all five SSTR subtypes in glioma and meningioma samples using Northern blot analysis and RT-PCR techniques and described that SSTR2 mRNA was the most abundantly expressed in both meningiomas and glioma samples." (PMID 38203605, 2023). "Biopsy-controlled studies have validated SSTR2 PET/CT as a highly sensitive tool for detecting meningioma tissue and distinguishing between tumor and tumor-free tissue, which is superior to MRI." (PMID 37642702, 2023). "In 21 meningioma patients the authors found a significant positive correlation between SUVmax and SSTR2 expression and by analysing locally different biopsies a SUVmax cut off value of 2.3 was set to define tumorous tissue." (PMID 37707754, 2023). "67.7% of meningiomas developed in female patients expressed somatostatin receptor SSTR-2/SSTR-2a subtype (95% CI: 59.7; 75.7) versus 77.4% of meningiomas in males (95% IC: 48.2; 100)." (PMID 36765937, 2023). "Studies have shown the use of 68Ga-DOTATATE, which recognizes SSTR2 and is being used clinically to evaluate or identify meningioma." (PMID 38203605, 2023).
meningioma (continued). "Somatostatin receptor type 2 (SSTR2) is ubiquitously expressed in up to 100% of meningiomas and can be addressed by radiolabeled SSTR2 ligands such as [68Ga]Gallium-DOTA-TATE, [68Ga]Gallium-DOTA-TOC, and most recently [18F]SiTATE." (PMID 37642702, 2023). "74.4% of grade 1 meningiomas expressed somatostatin receptor SSTR-2/SSTR-2a subtype compared to 94.7% of grade 2 (95% CI: 47.9–100 and 95% CI: 84.2–100)." (PMID 36765937, 2023). "Growing evidence supports the idea that SSTR2, in comparison to other meningioma markers, is more sensitive in the diagnosis of meningioma." (PMID 38203605, 2023). "Four ongoing clinical trials are currently evaluating [68Ga]Ga-DOTATOC and [68Ga]Ga-DOTATATE in patients with meningiomas, pituitary adenomas, and other SSTR2-positive brain tumors." (PMID 35740591, 2022). "As the majority of meningiomas express SSTR2, it is expected that meningiomas also have uptake by 68GA PSMA-11." (PMID 36179256, 2022). "Gallium-68-DOTATATE PET/CT which targets the somatostatin receptor 2 (SSTR2) has shown utility in meningioma radiographic diagnosis and distinguishing from other pathologies." (PMID 36033542, 2022). "Paragangliomas and meningiomas strongly express SSTR2 on tumor cells, providing a rationale for the binding and accumulation of SSTR targeting agents such as DOTATATE." (PMID 35546652, 2022). "[68Ga]Ga-DOTA-SSTR PET studies were mostly required to confirm the diagnosis of meningiomas (owing to their high SSTR2 expression and tracer uptake) or evaluate their extent of bone invasion, and improve volume contouring for better radiotherapy planning." (PMID 35740591, 2022). "Since almost all meningiomas overexpress SSTR-2, identification of residual tumor even in the mm range is feasible by combining the radiotracer SSTR-2 ligand Ga-68 DOTATOC and PET-MRI performed on a high-resolution research tomograph." (PMID 36010988, 2022). "A visual scoring system has been devised to further validate such a technique and differentiate better meningiomas from other tumors expressing SSTR-2 (breast cancer, thyroid cancer, Merkel cell carcinoma, lymphoma)." (PMID 33804251, 2021). "Fluorescence showed a positive trend with SSTR2 expression and therefore facilitated in distinction between meningioma and dura mater tissue in all meningioma types." (PMID 34633509, 2021). "In accordance with previous immunohistochemical studies, the majority of meningiomas expressed SSTR2." (PMID 34830858, 2021). "The correlation between the responses of benign meningioma and aggressive meningioma with the SSTR2 ADC will also be evaluated." (PMID 34063284, 2021). "As regards meningioma cells, SSTR2 is the predominant SSTR subtype, and it is present in 90% of meningiomas, therefore allowing interesting clinical applications for both diagnostic and therapeutic purposes in these tumors." (PMID 34577572, 2021). "[68Ga]-DOTATATE binds to SSTR2 on the cell surface of meningiomas, with high specificity, serving as an imaging biomarker for the detection of meningiomas." (PMID 35155210, 2021). "Meningiomas, the most common primary intracranial tumor, are vascular neoplasms that express somatostatin receptor-2 (SSTR2)." (PMID 35155210, 2021). "We and others previously demonstrated overexpression of SSTR2 on all meningioma grades, making it a promising biomarker for binding." (PMID 33768405, 2021). "In the present study, we developed a possible tracer for meningiomas that is directed against the somatostatin receptor subtype 2 (SSTR2)." (PMID 33768405, 2021). "Our study showed that the anti-SSTR2 ADC can effectively target meningioma and inhibit the tumor proliferation with minimal toxicity." (PMID 34063284, 2021). "The objective of this study was to develop and evaluate an ADC-based targeted therapy to treat aggressive meningiomas overexpressing SSTR2." (PMID 34063284, 2021).
meningioma (continued). "The highly frequent expression of SSTR2 in meningiomas has also been confirmed by other techniques, such as reverse transcription polymerase chain reaction (RT-PCR), Western blot and Northern blot." (PMID 34830858, 2021). "The flow cytometry analysis showed that the anti-SSTR2 mAb had a high binding rate of >98% to meningioma CH157-MN cells but a low binding rate of <5% to the normal arachnoidal AC07 cells." (PMID 34063284, 2021). "Despite these achievements, it is imperative to develop a targeted therapy to treat SSTR2-positive low- and high-grade meningiomas." (PMID 34063284, 2021). "The absence of psammoma bodies have previously been reported as a negative prognostic factor, and these results are in accordance with our finding of SSTR2 being more expressed in WHO grade 2 meningiomas." (PMID 34830858, 2021). "Meningiomas have been reported to commonly overexpress somatostatin receptor type 2 (SSTR2), and this property can be used to back up structural imaging with a biological study." (PMID 34572933, 2021). "This study has developed and evaluated an anti-SSTR2 monoclonal antibody–drug conjugate for meningioma-targeted therapy." (PMID 34063284, 2021). "In our series of meningiomas, the expression of SSTR2 and -5 was significantly different depending on meningioma subtype." (PMID 34830858, 2021). "SSTR2-targeted PET/CT should be a standard in the planning of curative radiation in pre-operated meningioma." (PMID 34572933, 2021). "SSTRs, and especially SSTR2, are useful in the diagnostics of meningiomas, even though their prognostic value appears limited." (PMID 34830858, 2021). "Meningioma expresses high levels of SSTR2, allowing the use of radiolabeled somatostatin analogs for imaging and therapeutic purposes." (PMID 34577572, 2021). "With an increased incidence in females and ∼100% of meningiomas having somatostatin receptor 2 (SSTR2), ~88% progesterone receptors, ~40% estrogen receptors, and ~40% androgen receptors, it was thought that hormones played a slight role in tumor growth." (PMID 33801089, 2021). "Lastly, the clinical meningioma specimens (representing different WHO grades) all expressed SSTR2 and showed 800CW-TATE-specific fluorescence staining." (PMID 33768405, 2021). "Taken together, the developed anti-SSTR2 ADC has a great potential to treat SSTR2-positive meningioma by the targeted delivery of a potent small molecule with minimal side effects." (PMID 34063284, 2021). "A recent study evaluated Ac-Lys0(800CW)Tyr3-ocreotate (800CW-TATE), targeting somatostatin receptor subtype 2 (SSTR2), as a potential tracer in fluorescence-guided surgery of meningiomas." (PMID 34633509, 2021). "Our next step in the development of 800CW-TATE for MFGS in meningiomas will be the clinical evaluation of this tracer in patients with intracranial meningiomas, aiming to add another SSTR2-directed approach to the treatment of this type of tumors." (PMID 33768405, 2021). "Tyr3-octreotate, a previously generated peptide-analogue with a high affinity for SSTR2, served as the meningioma specific binding part." (PMID 33768405, 2021). "The meningioma targeting, circulation stability, toxicity, and anti-tumor efficacy of SSTR2 ADC were evaluated using cell lines and/or an intracranial xenograft mouse model." (PMID 34063284, 2021). "Among these receptors, the overexpression of SSTR2 was the most frequent in meningiomas compared with the other SSTR subtypes." (PMID 33014821, 2020). "Pertinent literature is reviewed to summarize the recent collective knowledge and understanding of SSTR2’s clinical significance in meningioma in this review." (PMID 33014821, 2020). "SSTR2 offers novel ideas and approaches in the diagnosis, treatment, and prognostic prediction for meningioma, but more and further studies are required." (PMID 33014821, 2020). "In recent years, accumulating studies have reported the correlation between SSTR2 expression and meningiomas." (PMID 33014821, 2020).
meningioma (continued). "Single photon emission CT (SPECT) somatostatin receptor scintigraphy (SRS) using 111In-octreotide is another valuable tool for the diagnoses of meningiomas based on the general expression of SSTR2 in all meningiomas." (PMID 33014821, 2020). "SSTR2 is therefore extensively studied as a marker and target for the diagnosis and treatment of meningioma." (PMID 33014821, 2020). "SSTR2 expressed in almost all meningiomas, which provides novel ideas and approaches in the diagnosis, treatment, and prognostic prediction for meningiomas." (PMID 33014821, 2020). "Certain progress regarding the clinical significance of SSTR2 in meningioma has been made in the past few decades." (PMID 33014821, 2020). "In this context, SSTR-PET imaging can play a fundamental role in the visualization of residual meningioma tissue, considering the high levels of SSTR-2 expression in meningiomas and the favourable target-to-background ratio." (PMID 31546734, 2019). "Somatostatin receptor-2 expression has recently been described in a variety of canine meningioma subtypes, a finding that is supported by RNAseq data analysis of canine meningioma that revealed increased expression of somatostatin receptors." (PMID 31788444, 2019). "The potential of SSTR-2 was analysed in a translational model using newly generated patient-derived 3D meningioma cultures." (PMID 29858948, 2018). "This indicates that specific fluorescence in an experimental setting can be performed for the further development of targeted fluorescence guided meningioma surgery and near-infrared fluorescent tracers targeting SSTR-2." (PMID 29858948, 2018). "We identified SSTR-2 as the most suitable biomarker for targeted fluorescence-guided meningioma surgery by applying TMA-IHC and TASC." (PMID 29858948, 2018). "As far as we know, this is the first time that the expression SSTR-2 has been determined in in vitro meningioma cultures using IHC." (PMID 29858948, 2018). "In vitro cultures were established to further explore the potential of SSTR-2 as a meningioma-specific marker in a translational model." (PMID 29858948, 2018). "Because of the receptor targeting, DOTATOC is known to be more specific for meningiomas with the known limitation in areas close to the parasellar region since the pituitary gland expresses SSTR2." (PMID 29110720, 2017). "The observation that meningioma cells overexpress the somatostatin receptor 2 (SSTR2) was the rationale to retrospectively analyze how far DOTATOC-PET/CT is helpful to improve target volume delineation for IMRT." (PMID 24141602, 2014). "Meningiomas express a large variety of receptors, including progesterone, androgens, growth factor, prolactin, dopamine, and somatostatin receptor subtype 2 (SSTR2)." (PMID 25369268, 2014). "Meningiomas express relatively high levels of SSTR2, thus making them ideal targets for functional imaging and radionuclide therapy with radiolabeled somatostatin analogues." (PMID 25369268, 2014). "Meningiomas visualization with 111In-octreotide depends on the expression of SSTR2 on meningioma cells—as shown by the reverse transcriptase polymerase chain reaction—, as well as on the tumor volume." (PMID 22623896, 2012). "Meningiomas, which originate from the arachnoid layer of the leptomeninx, usually have a high SSTR2 density." (PMID 22623896, 2012). "Meningiomas particularly show high levels of somatostatin receptor expression (SSTR2) resulting in a high tracer uptake." (PMID 19922642, 2009). "Thus, SSTR2 is considered a hypothetical treatment target in meningiomas, with a score of IIIA on the European Society for Medical Oncology Scale for Clinical Actionability of Molecular Targets." (PMID 40774695, 2026). "A nuanced approach with SSTR2-targeted theranostics has gained traction for use in meningiomas." (PMID 40149634, 2025). "SSTR2 expression has been reported in 100% of meningiomas in pathology studies." (PMID 41497451, 2025).
meningioma (continued). "Importantly, SSTR-2 expression in meningiomas can be pre-operatively assessed by positron emission tomography (PET) using radiolabeled SSTR-2 ligands, such as 68Ga-DOTATE or 68Ga-DOTATOC." (PMID 40430568, 2025). "Furthermore, 177Lu DOTATATE, another agent that targets SSTR2, had been employed in radionuclide therapy for meningiomas." (PMID 40170861, 2025). "One type of receptor for this hormone, the somatostatin receptor 2 (SSTR2), is expressed in virtually all meningioma cells, with the exact importance of this finding still being unknown." (PMID 38632533, 2024). "One of the first examples was [68Ga]Ga-DOTA-TOC, a tracer that binds to somatostatin receptor 2 (SSTR2)-expressing tumors, such as neuroendocrine carcinomas or meningiomas, and it is also used for therapy in DOTA-TOC-positive tumors labeled with beta emitters as 90Y or 177Lu." (PMID 39770483, 2024). "Hormonal factors may play a role in meningioma development since these tumors express hormone receptors such as somatostatin receptor 2 (SSTR2), progesterone, estrogen, and androgen." (PMID 39618617, 2024). "Somatostatin receptor subtype 2 (SSTR2) is expressed in canine meningioma." (PMID 39055601, 2024). "This observed pattern of DNA damage induction by PRRT could be detected for six meningioma samples staining strongly positive for SSTR2." (PMID 39061156, 2024). "(2019), which used the same antibody as us for the screening of 21 canine meningiomas, the detection rate of SSTR2 by IHC was lower (81%), which might be related to the larger number of cases and grade III meningiomas in their study." (PMID 39011594, 2024). "Also, high expression of SSTR2 and -3 has been shown in meningioma after partial resection with tumour recurrence." (PMID 38203605, 2023). "Probably, baseline SSTR2 expression may play a key role in the correct selection of patients with aggressive meningiomas to address to RLT." (PMID 37111596, 2023). "The SSTR-2/SSTR-2a subtype is the most frequently expressed in meningiomas." (PMID 36765937, 2023). "Within our cohort, we confirmed that all four approaches to [68Ga]-DOTATATE PET quantification (absolute SUV, SUVRsss, SUVRpit, and SUVRnorm) aid in the differentiation of meningioma from post-treatment changes, confirming the reliability of the SSTR2 targeted imaging in meningioma patients." (PMID 35661809, 2022). "One of them is somatostatin receptor 2, which can be found in most meningiomas." (PMID 33899156, 2022). "The majority of meningiomas are now known to highly express somatostatin receptor-2 (SSTR2)." (PMID 34399805, 2021). "In this study, we found a strong, significant correlation between the DCE-MRI perfusion parameter Kep and [68Ga]-DOTATATE SUV in WHO Grade 2/3 meningiomas, which suggests biological differences in the relationship between tumor vascularity and SSTR2 expression in higher-grade meningiomas." (PMID 35155210, 2021). "The tracer bound specifically to SSTR2-positive meningioma tissues representing all WHO grades." (PMID 33768405, 2021). "This study demonstrated that the anti-SSTR2 ADC can target meningioma and reduce the tumor growth." (PMID 34063284, 2021). "SSTR2 presents as an especially promising candidate for improving meningioma diagnostics." (PMID 34830858, 2021). "SSTR2 expression was found to be characteristic in meningiomas." (PMID 34830858, 2021). "In this regard, it is important to underline that intraarterial administration of the radiolabeled somatostatin analog may increase the efficacy of PRRT in meningiomas with low levels of SSTR2, as suggested in an interesting report by Braat and collaborators." (PMID 34577572, 2021). "Moreover, fresh meningioma samples (Online Resource 5) containing adjacent non-tumorous dura mater as well as meningioma tissue were analyzed for tracer binding and SSTR2 expression in order to evaluate selectivity for meningioma tissue." (PMID 33768405, 2021).